ITGA8 (integrin subunit alpha 8)
Description:
Integrin alpha-8/beta-1 functions in the genesis of kidney and probably of other organs by regulating the recruitment of mesenchymal cells into epithelial structures. It recognizes the sequence R-G-D in a wide array of ligands including TNC, FN1, SPP1 TGFB1, TGFB3 and VTN. NPNT is probably its functional ligand in kidney genesis. Neuronal receptor for TNC it mediates cell-cell interactions and regulates neurite outgrowth of sensory and motor neurons.
Tractability: Antibody: UniProt places it where antibodies can reach, with high confidence; its Gene Ontology location is reachable by antibodies, with high confidence; UniProt predicts a signal peptide or a membrane-spanning region; the Human Protein Atlas places it where antibodies can reach. PROTAC: ubiquitination databases record sites on it.
Gene: Protein-coding gene on chromosome 10 (15,513,954 to 15,719,936, reverse strand). Ensembl gene ENSG00000077943.
Subcellular location: Membrane; Cell membrane
Subcellular location (Human Protein Atlas): Plasma membrane
Pathways (Reactome):
Extracellular matrix organization: ECM proteoglycans; Integrin cell surface interactions; Molecules associated with elastic fibres
Developmental Biology: Formation of the ureteric bud
Signal Transduction: TGF-beta receptor signaling activates SMADs
Gene Ontology:
Molecular function: signaling receptor activity
Biological process: cell-matrix adhesion; kidney development; mesodermal cell differentiation; substrate adhesion-dependent cell spreading; cell-cell adhesion; integrin-mediated signaling pathway; cell adhesion; cell differentiation; cell-substrate adhesion; establishment of protein localization; formation of primary germ layer; positive regulation of transcription by RNA polymerase II; smooth muscle cell differentiation; smooth muscle tissue development; tissue development
Cellular component: cell surface; endoplasmic reticulum; focal adhesion; integrin alpha8-beta1 complex; integrin complex; plasma membrane; apical part of cell; membrane
Genetic constraint (gnomAD): Loss-of-function variants: 59 observed, 91.54 expected, observed/expected ratio (o/e) 0.64, 90% interval 0.52 to 0.8. The upper end of that interval is the gene's LOEUF score, 0.8, which puts it in group 3 of 6, group 1 being the genes least tolerant of losing a copy. Missense variants: 1,056 observed, 989.63 expected, observed/expected ratio (o/e) 1.07, 90% interval 1.01 to 1.12. Synonymous variants: 396 observed, 366.36 expected, observed/expected ratio (o/e) 1.08, 90% interval 1 to 1.17.
Homologues: Orthologues: chimpanzee ITGA8 (99% identical), macaque ITGA8 (97% identical), rabbit ITGA8 (91% identical), guinea pig ITGA8 (90% identical), pig ITGA8 (89% identical), dog ITGA8 (89% identical), mouse Itga8 (89% identical), rat Itga8 (89% identical), tropical clawed frog itga8 (72% identical), zebrafish itga8 (62% identical), Caenorhabditis elegans pat-2 (28% identical), Drosophila melanogaster if (27% identical), and 3 more. Paralogues in human: ITGAV (47% identical), ITGA5 (44% identical), ITGA2B (38% identical), ITGA7 (27% identical), ITGA6 (25% identical), ITGA3 (24% identical), ITGA4 (24% identical), ITGA9 (24% identical), ITGA2 (23% identical), ITGA11 (22% identical), ITGAM (22% identical), ITGA1 (21% identical), and 5 more.
Diseases named in the same sentence as ITGA8 in open-access papers:
ITGA8 is named in the same sentence as 66 diseases in open-access papers, as found by Europe PMC text mining. Sharing a sentence is not in itself a finding about the gene and the disease. The quoted sentences say what the papers report.
lung adenocarcinoma (6 papers, 2018 to 2026). A carcinoma that arises from the lung and is characterized by the presence of malignant glandular epithelial cells. "used a genome‐wide CRISPR–Cas9 library screen to identify integrin subunit alpha 8 (ITGA8) as a gene that increases the sensitivity of lung adenocarcinoma cells to EGFR‐TKIs." (PMID 41537447, 2026). "Survival analysis of patients with lung adenocarcinoma revealed that higher ITGA8 expression had better prognosis." (PMID 36911684, 2023). "ITGA8 enhances lung adenocarcinoma sensitivity to abivertinib." (PMID 41537447, 2026). "Some researchers have also suggested that ITGA8 was considerably lowly expressed in lung adenocarcinoma (LUAD), and ITGA8 could be a potential prognostic biomarker in LUAD patients." (PMID 36837559, 2023). "Meanwhile, key genes extensively indicated significant prognostic significance, and CBX7, ITGA8, ADRB2, and CAV1 were significant favorable factors for lung adenocarcinoma." (PMID 37123398, 2023).
lung fibrosis (6 papers, 2018 to 2025). "Genes such as arginase 1 (ARG1), were shown to be dysregulated in the alveolar macrophages during PRRSV infections, and integrin subunit alpha 8 (ITGA8) has been implicated in lung fibrosis." (PMID 33187194, 2020). "We therefore tested this hypothesis in mice with Pdgfrb-Cre and floxed alleles of Itga8 in bleomycin-induced lung fibrosis." (PMID 29813125, 2018). "We confirmed ITGA8 was decreased in silica-induced pulmonary fibrosis, and the role of ITGA8 in silica-induced needs further research." (PMID 33119648, 2020). "At the same time, they overexpressed genes of the WNT pathway, TBX4, and ITGA8, which have been demonstrated to play a part in lung fibrosis." (PMID 32492951, 2020). "Since ITGA8 expression is restricted to stromal cells in the lung, we investigated the functional role of ITGA8 expression in myofibroblasts in lung fibrosis." (PMID 29813125, 2018). "Other genes activated in CF-HLF as in lung fibrosis were: TBX4 and ITGA8." (PMID 32492951, 2020). "Based on these data, we conclude that ITGA8 deletion from PDGFRβ+ stromal cells does not affect lung fibrosis in the bleomycin model." (PMID 29813125, 2018). "Although to our knowledge no one has assessed lung fibrosis in the global KO, our results show that ITGA8 in PDGFRβ+ cells is dispensable in the bleomycin model." (PMID 29813125, 2018). "Though ITGA8 exhibits LAP-TGFβ binding similar to other alpha integrins in the family, expression of ITGA8 in PDGFRβ+ cells does not appear to have a major biological role in lung fibrosis." (PMID 29813125, 2018). "Studies of fibrosis in kidneys suggest ITGA8 signaling might attenuate renal fibrosis, but the functional role of ITGA8 in lung fibrosis has never been studied." (PMID 29813125, 2018). "ITGA8 deletion increased COL1A1 production during lung fibrosis in vitro, but did not affect pulmonary fibrosis in the bleomycin animal model." (PMID 33119648, 2020).
renal fibrosis (6 papers, 2016 to 2025). A final common manifestation of a wide variety of chronic kidney diseases characterized by glomerulosclerosis and tubulointerstitial fibrosis. "We have previously shown that renal fibrosis after UUO is more severe in mice with a deficiency for the Itga8 chain." (PMID 26938996, 2016). "In unilateral ureteral obstruction Itga8 is de novo expressed in the tubulointerstitium and a deficiency of Itga8 results in more severe renal fibrosis after unilateral ureteral obstruction." (PMID 26938996, 2016). "This was also observed in fibroblasts in our model of renal fibrosis: Interstitial cells of Itga8-deficient kidneys after UUO are more frequently positive for α-smooth muscle actin than interstitial cells from wild types." (PMID 26938996, 2016). "Prior studies have demonstrated that ITGA8 plays a role in promoting renal fibrosis by influencing fibroblast activation and immune cell infiltration." (PMID 38355637, 2024). "The increased expression levels of renal fibrosis-related genes (Grem2, Id3, Fst, Dcn) and renal damage-related genes (Runx1, Vtn, Clo6a2, Tnxb, Itga8, Timp2, Fgfr2, Fgf9) further supported the idea that miPEP31 deficiency exacerbated Ang II-induced kidney inflammation." (PMID 38992718, 2024). "However, in Cre+ cells, mRNA levels of collagen were elevated over that in Cre-, consistent with findings of increased renal fibrosis in ITGA8 knockout animals." (PMID 29813125, 2018). "We therefore hypothesized that the de novo expression of Itga8 in tubulointerstitial cells in UUO might attenuate renal fibrosis by reducing tubulointerstitial cell proliferation and/or apoptosis." (PMID 26938996, 2016). "Mice with a deficiency for Itga8 show more macrophages and more T-cells infiltrating the kidney after UUO than wild type mice, which might contribute to the more severe renal fibrosis in these mice." (PMID 26938996, 2016). "Taken together our findings suggest that the increased renal fibrosis detected in Itga8-deficient mice is not a consequence of an augmented tubulointerstitial cell turnover, but more likely due to a higher degree of fibroblast activation and/or to more macrophage and T-cell infiltration." (PMID 26938996, 2016). "Renal fibrosis and congenital abnormalities of the kidney and urinary tract (CAKUT) are two renal conditions that may be influenced by dysregulation of ITGA8 expression or function." (PMID 39064873, 2024). "Why then does a lack of Itga8 aggravate renal fibrosis after UUO?" (PMID 26938996, 2016).
atherosclerosis (3 papers, 2017 to 2022). A disease characterized by the build-up of fatty material and calcium deposition in the arterial wall resulting in partial or complete occlusion of the arterial lumen. "We recently described accelerated atherosclerosis as well as marked renal injury in Apoe−/− mice deficient in the mesenchymal integrin chain Itga8 (Itga8−/−)." (PMID 28572914, 2017). "The role of ITGA8 has been linked to aortic calcification in a murine model of atherosclerosis." (PMID 36386365, 2022). "In male Apoe-deficient mice, previous studies showed that a lack of the vascular integrin Itga8 is associated with aggravated atherosclerosis and the development of renal injury." (PMID 28572914, 2017). "SMC1.2, strongly expressed ITGA8, required for maintenance of SMC contractile phenotype, and ATP10A, suggesting vascular stiffness and increasing diastolic dysfunction Methylation of the ATP10A locus in SMC decreases with age and atherosclerosis." (PMID 35926050, 2022).
breast carcinoma (3 papers, 2022 to 2023). "Interestingly, a tumor-suppressive role of ITGA8, mainly through ITGA8 silencing by gene hypermethylation, has been reported in breast cancer and renal cell carcinoma." (PMID 36361816, 2022). "ITGA8 has been proven to be correlated with favorable outcomes in patients with basal-like and HER2+ breast cancer and colon cancer." (PMID 35557945, 2022).
colon cancer (3 papers, 2021 to 2024). "In addition, Itga8 expression may be a potential diagnostic marker of colon cancer." (PMID 34034704, 2021).
glomerular disease (3 papers, 2020 to 2021). "Increased ITGA8 expression has the potential to be a clinical marker of glomerular disease prognosis since ITGA8 supports adhesion of mesangial cells, reduces cell proliferation, protects against apoptosis, and facilitates phagocytosis." (PMID 34222276, 2021). "In addition, anti-ITGA8 therapies have been reported to play a role in the treatment of lupus and other glomerular diseases." (PMID 34660316, 2021).
glomerulonephritis (3 papers, 2018 to 2020). A renal disorder characterized by damage in the glomeruli. "Deficiency of ITGA8 worsened tubulointersititial fibrosis and delayed healing in a model of glomerulonephritis." (PMID 33119648, 2020). "In the kidney, lack of ITGA8 worsens tubulointersititial fibrosis and delays healing in a model of glomerulonephritis." (PMID 29813125, 2018).
Hypertension (3 papers, 2018 to 2024). The presence of chronic increased pressure in the systemic arterial system. "Therefore, fibronectin variants with reduced or lacking binding affinity to ITGA8 may lead to lower nephron number and predispose to arterial hypertension and CKD." (PMID 38563997, 2024). "In the heart, however, global deletion of ITGA8 does not change the extent of hypertension-induced fibrosis in KO mice, despite the upregulation of ITGA8 in in this disease model." (PMID 29813125, 2018).
liver fibrosis (3 papers, 2021 to 2026). "In addition, the same authors found that ITGA8 was minimally expressed in healthy liver, underlying its relevance with liver fibrosis." (PMID 34262480, 2021). "Corresponded with the current results, up-regulated ITGA8 was previously reported in broiler breast muscle affected by WS abnormality, and in specimen of 90 patients with hepatic fibrosis." (PMID 34262480, 2021). "Furthermore, Itga8 expression was shown to be elevated in liver fibrosis specimens and has been identified as a specific cell surface marker of perivascular mesenchymal cells in the developing liver." (PMID 41535231, 2026). "Furthermore, ITGA8 was upregulated in specimens from 90 patients with liver fibrosis, indicating the relevance of our findings to liver fibrosis in people." (PMID 33433924, 2021).
ovarian carcinoma (3 papers, 2012 to 2024). A malignant neoplasm originating from the surface ovarian epithelium. "Besides regulating ITGA8 expression, exosomal RNA-mediated regulation of ITGA8 function might be implicated in the pathogenesis of ovarian cancer." (PMID 38755265, 2024). "Taken together, M2 macrophage-derived exosomes enhance malignancy in ovarian cancer by delivering circTMCO3 and targeting the miR-515-5p/ITGA8 axis." (PMID 38755265, 2024). "To conclude, miR-515-5p represses proliferation, migration, invasion, and epithelial-mesenchymal transition (EMT) through suppression of ITGA8 in ovarian cancer." (PMID 38755265, 2024). "Further investigation demonstrated that M2 macrophage-derived exosomal circTMCO3 promoted the malignancy by targeting the miR-515-5p/ITGA8 axis in ovarian cancer." (PMID 38755265, 2024). "This study shows that M2 macrophage-derived exosomes promote malignancy in ovarian cancer cells by delivering circTMCO3 and targeting the miR-515-5p/ITGA8 axis." (PMID 38755265, 2024). "ITGA8 expression was negatively correlated with miR-515-5p expression but positively correlated with circTMCO3 expression in ovarian cancer." (PMID 38755265, 2024). "Here, we firstly demonstrated that M2 macrophage-derived exosomal circTMCO3 sponged miR-515-5p and relieved its inhibitor effect on ITGA8 expression, thereby promoting the malignancy and progression of ovarian cancer." (PMID 38755265, 2024). "CHL1 and ITGA8 were identified as specific potential biomarkers for renal and ovarian cancer, respectively." (PMID 25997610, 2015). "Thus, M2 macrophage-derived exosomes promote malignancy by delivering circTMCO3 and targeting the miR-515-5p/ITGA8 axis in ovarian cancer." (PMID 38755265, 2024). "We showed ITGA8 as a downstream target of miR-515-5p in ovarian cancer." (PMID 38755265, 2024). "We then examined whether exosomal circTMCO3-mediated regulation of malignancy in ovarian cancer was dependent on the miR-515-5p/ITGA8 axis." (PMID 38755265, 2024). "miR-515-5p inhibits ovarian cancer malignancy via directly downregulating ITGA8." (PMID 38755265, 2024). "Likewise, EHD2, ITGA8 and EMP1 has also been identified as tumor suppressor genes that when altered is associated with highly malignant ovarian cancers and germ cell tumors." (PMID 22737227, 2012). "Therefore, we hypothesized that M2-derived exosomal circTMCO3 might regulate malignant behaviors in ovarian cancer via sponging miR-515-5p and upregulating ITGA8." (PMID 38755265, 2024). "Therefore, miR-515-5p represses ITGA8 expression via binding to its 3′ UTR in ovarian cancer." (PMID 38755265, 2024).
renal agenesis (3 papers, 2020 to 2024). Renal agenesis (RA) is a form of renal tract malformation characterized by the complete absence of development of one or both kidneys (unilateral RA or bilateral RA respectively), accompanied by absent ureter(s). "Similar to GDNF deletion, loss of ITGA8 in mouse leads to impaired UB outgrowth in the MM and results in renal agenesis." (PMID 38563997, 2024). "In addition, mutations of ITGA8 have been described as a genetic cause of bilateral renal agenesis in humans." (PMID 38563997, 2024). "Next to the detrimental phenotypes provided by loss of GDNF or ITGA8, alterations in kidney development do not always have to result in renal agenesis but can affect the final kidney size and number of nephrons and glomeruli." (PMID 38563997, 2024).
visceral myopathy (3 papers, 2022 to 2025). "The Itga8-CreERT2 model that we used for specific deletion of Srf in vascular SMCs was developed to circumvent lethal visceral myopathies often seen with deletion strategies that target all SMCs." (PMID 40081573, 2025). "Itga8 is preferentially expressed in vascular over visceral SMCs, and the Itga8-Cre model evaded a severe visceral myopathy when used to delete serum response factor (SRF)." (PMID 37561588, 2023). "In conclusion, Itga8-CreERT2 provides an effective method to delete genes in lymphatic SM, avoiding potentially lethal visceral myopathy and allowing comparative studies of lymphatic contractile function in both male and female mice." (PMID 36714313, 2022). "Discussion: Our results demonstrate that Itga8-CreERT2 can be used to effectively delete genes in lymphatic smooth muscle while avoiding potentially lethal visceral myopathy and allowing comparative studies of lymphatic contractile function in both male and female mice." (PMID 36714313, 2022).
dilated cardiomyopathy (2 papers, 2013 to 2025). Cardiomyopathy which is characterized by dilation and contractile dysfunction of the left and right ventricles. "Moreover, in dilated cardiomyopathy pathway core enrichment, integrins (Itga1, Itga10, Itga8 and Itgb6) and cellular components of troponin system (Tnni3, Tnnc1 and Tnnt2) appeared modulated, besides Cox and Myh genes." (PMID 24252798, 2013).
fibrosis (2 papers, 2018 to 2020). the formation of excess fibrous connective tissue in an organ or tissue in a reparative or reactive process. "In the lung, ITGA8 expression was restricted to interstitial stromal cells, and that was increased in bleomycin-induced fibrosis." (PMID 33119648, 2020). "In the lung, ITGA8 expression is especially enriched in interstitial stromal cells following bleomycin-induced fibrosis." (PMID 29813125, 2018). "ITGA8 knockout animals experience early postnatal mortality due to defects in nephrogenesis, which limits their utility in adult fibrosis models." (PMID 29813125, 2018).
gastric cancer (2 papers, 2020 to 2022). A primary or metastatic malignant neoplasm involving the stomach. "Out of the most significantly down-regulated genes in BM, tumor suppressive implications have been reported for myosin heavy chain 11 (MYH11) in gastric cancer and integrin subunit α 8 (ITGA8)." (PMID 36361816, 2022).
glioma (2 papers, 2024 to 2025). A benign or malignant brain and spinal cord tumor that arises from glial cells (astrocytes, oligodendrocytes, ependymal cells). "Additionally, these data revealed that ITGA8's expression is reduced in low‐grade glioma, glioblastoma, and meningioma compared to the adult control brain." (PMID 41085070, 2025). "In MAN1C1-expressing glioma cells, the presence of highly glycosylated receptors, such as CD44 and integrins (ITGB1, ITGAV, ITGA8, ITGAB1) facilitates this interaction." (PMID 39333557, 2024).